FABP1 (fatty acid binding protein 1)
Diseases named in the same sentence as FABP1 in open-access papers (continued):
Sharing a sentence is not in itself a finding about the gene and the disease.
diabetic nephropathy (19 papers, 2012 to 2026). "A plasma FABP1 concentration of >33.8 ng/mL was associated with diabetic nephropathy, with a sensitivity of 75.3% and specificity of 75.6%." (PMID 32922199, 2020). "In the present study FABP1 levels were associated with diabetic nephropathy, and plasma FABP1 levels increased in parallel with the decline in eGFR (β = -0.337, p <0.0001)." (PMID 32922199, 2020). "Furthermore, a previous study suggested that the serum FABP1 level in the renal tubules is associated with glomerular disease and FABP1 plays a protective role in renal tubulointerstitial injury and glomerular injury of diabetic nephropathy." (PMID 36277716, 2022). "Recently, increased FABP1 levels in human subjects has been identified as a biomarker in diabetic nephropathy." (PMID 35252766, 2022). "An altered mitochondrial β-oxidation was shown in early stages of normoalbuminuric diabetic kidney disease patients, and increased urinary levels of FABP1 suggested an increased incidence of progression of CKD and cardiovascular disease events." (PMID 34356333, 2021). "Studies with long-term follow-up are needed to clarify the role of FABP1 and FABP2 in association with diabetic nephropathy." (PMID 32922199, 2020). "Further studies are needed to elucidate the exact role of FABP1 in patients with diabetic nephropathy." (PMID 32038102, 2020). "Increasing levels of FABP1 and FABP2 showed a significant linear trend and were independently associated with diabetic nephropathy, especially when concentrations were analyzed both by tertile and by a continuous variable." (PMID 32922199, 2020). "The plasma FABP1 and FABP2 concentrations were significantly associated with diabetic nephropathy even after controlling for anthropometric variables, fasting glucose, lipid profile, and smoking status." (PMID 32922199, 2020). "The cross-sectional design limits our ability to infer a causal relationship between increased plasma FABP1 and FABP2 levels and diabetic nephropathy." (PMID 32922199, 2020). "In conclusion, this study demonstrated that plasma FABP1 and FABP2 levels were significantly associated with diabetic nephropathy." (PMID 32922199, 2020). "The results showed that in patients with type 1 diabetes, urinary FABP1 concentrations increased with the progression of diabetic nephropathy and were higher in normoalbuminuric patients than in control subjects 39,40." (PMID 32038102, 2020). "The ROC curve to detect diabetic nephropathy revealed an area under the curve (AUC) of 0.780 (95% CI: 1.019-1.045, p <0.0001) for FABP1." (PMID 32922199, 2020). "In terms of CKD, animal and clinical studies have documented the usefulness of FABP1 as a marker for diabetic kidney disease." (PMID 32922199, 2020). "Increasing concentrations of FABP1 and FABP2 were independently and significantly associated with diabetic nephropathy." (PMID 32922199, 2020). "Multiple logistic regression analysis revealed FABP1 and FABP2 as an independent association factor for diabetic nephropathy, even after full adjustment of known biomarkers." (PMID 32922199, 2020). "The results of the present study support the idea 29-31 that FABP1 may be a marker of diabetic nephropathy in patients with T2DM." (PMID 32922199, 2020). "Moreover, an increased concentration of plasma FABP1 and FABP2 was associated with diabetic nephropathy, even in a fully adjusted model." (PMID 32922199, 2020). "Furthermore, receiver operating characteristic curve analysis showed that a FABP1 level of >33.8 ng/mL and a FABP2 level of >2.8 ng/mL were associated with diabetic nephropathy." (PMID 32922199, 2020). "FABP1 plays an essential role in intracellular fatty acid transport and metabolism and may serve as a potential biomarker for tubular involvement in pediatric diabetic kidney disease." (PMID 42298045, 2026). "This may explain why our diabetic nephropathy patients had high plasma FABP1 levels." (PMID 32922199, 2020).
diabetic nephropathy (continued). "Furthermore, the ROC curves of FABP1 and FABP2 concentrations showed that a FABP1 concentration of >33.8 ng/mL was associated with diabetic nephropathy and a FABP2 concentration of >2.8 ng/mL were associated with diabetic nephropathy." (PMID 32922199, 2020). "Although the use of plasma FABP2 level as a single surrogate biomarker to predict diabetic nephropathy will be limited, it may be useful as one indicator in a multi-marker panel such as in combination with plasma FABP1 to better assess individuals suspected of having diabetic nephropathy." (PMID 32922199, 2020). "Demographic and potential metabolic confounding factors were analyzed with logistic regression to calculate the effects of FABP1 and FABP2 levels on diabetic nephropathy." (PMID 32922199, 2020). "FABP1 and FABP2 could be novel biomarkers of diabetic nephropathy." (PMID 32922199, 2020).
non-alcoholic fatty liver disease (18 papers, 2015 to 2025). "In addition, the measurement of liver-type fatty acid-binding protein (FABP1/L-FABP), was also included as this protein is associated with dyslipidemia (elevated plasma triglycerides) and non-alcoholic fatty liver disease (NAFLD), a condition commonly seen in FHTG subjects." (PMID 33588820, 2021). "FABP1 is downstream of the PPAR signaling pathway, and the silencing of FABP1 in the liver ameliorated hepatic oxidative stress and inflammation in a mouse model of nonalcoholic fatty liver disease." (PMID 40699771, 2025). "Similar results also showed that FABP1 levels were higher in patients with non-alcoholic fatty liver disease." (PMID 36005631, 2022). "Reduced levels of FABP1 in mice livers have been shown to be effective against nonalcoholic fatty liver disease (NAFLD)." (PMID 32038102, 2020). "FABP1 was reported to correlate with non-alcoholic fatty liver disease, and CYP2A13 was found to be involved in the development and progression of lung adenocarcinoma; however, neither of them was previously associated with NSLN metastasis." (PMID 26311227, 2015). "As an important endogenous cytoprotective agent, FABP1 reduces oxidative damage to hepatocytes and agonists in liver I/R and other injuries, whereas the downregulation of FABP1 expression protects against non-alcoholic fatty liver disease." (PMID 36077044, 2022). "FABP-1 has been suggested as a marker of kidney injury, since its concentration increases in such conditions of different etiology and lung injury, and is a predictive factor for nonalcoholic fatty liver disease (NAFLD)." (PMID 36144237, 2022). "These proteins were mainly involved in fatty acid metabolism (Fasn, Scd1, Fads2, Fdps, Plin2), fatty acid degradation (Ehhadh, Acsl1), PPAR signaling pathway (Fads2, Ehhadh, Acsl1, Fabp1), non-alcoholic fatty liver disease (Ehhadh, Pklr) and AMPK signaling pathway (Fasn, Scd1, Hnf4a)." (PMID 32210812, 2020). "CagA+ strains disrupt lipid metabolism, increasing non-alcoholic fatty liver disease, cardiovascular, and Alzheimer’s risks via PPAR interference, GBA1 demethylation, and altered FABP1/APOA1 expression, reversible by eradication." (PMID 41158522, 2025). "Dysregulation was established for FABP3 in cardiovascular disorders, FABP1, FABP2, FABP4 and FABP5 in non-alcoholic fatty liver disease and FABP5 and FABP7 in cancer." (PMID 30386187, 2018). "Cd36, Cidea, and Fabp1 are considered PPARA-dependent genes that are highly expressed under metabolic stress in liver and could be potential therapeutic targets for nonalcoholic fatty liver disease." (PMID 38786053, 2024).
Insulin resistance (15 papers, 2011 to 2024). Increased resistance towards insulin, that is, diminished effectiveness of insulin in reducing blood glucose levels. "The Multiple Regression Modeling for binary insulin resistance and the MetS associated with per SD increase in serum FABP1." (PMID 23144966, 2012). "We evaluated the possible association of polymorphisms of the FABP-1 gene with insulin resistance in the replication population." (PMID 22396741, 2012). "FABP1 levels remained an independent risk factor of insulin resistance assessed by binary Si (OR = 1.868 per SD unit, 95% CI [1.035–3.373], p = 0.038) after adjustment for age, sex, BMI, waist circumference, systolic blood pressure, serum triacylglycerol, total cholesterol, HDL- and LDL-cholesterol." (PMID 23144966, 2012). "The increased expression of FABP1 is mainly related to the occurrence of insulin resistance and the promotion of fatty acid transport." (PMID 36176635, 2022). "In this study, we investigated the relationship of serum FABP1 levels with parameters of adiposity and insulin resistance in Chinese young adults." (PMID 23144966, 2012). "In addition, the related fatty acids metabolism is also enriched in the PPAR signaling pathway or insulin resistance pathway, such as Fads2, Pparg, Acsl5, Fabp1 and Acacb." (PMID 37627267, 2023). "The OR in the second and third tertiles of FABP1 remained significant after adjustments for BMI, triglycerides, high-density lipoprotein cholesterol, HbA1C, homeostasis model assessment estimate of insulin resistance, white blood cell count, hepatic enzymes, and eGFR." (PMID 32038102, 2020). "There have been no reports on the association of serum FABP1 levels with insulin resistance in human." (PMID 23144966, 2012). "Our multiple regression modeling for insulin resistance suggested that lipids may mediate the relationship between FABP1 and insulin resistance." (PMID 23144966, 2012). "Moreover, the relationship between FABP1 and insulin resistance (reflected by binary Si) remains significant even after controlling for confounders." (PMID 23144966, 2012). "These novel findings suggest that serum FABP1 levels may act as a circulating biomarker of adiposity and insulin resistance-related metabolic diseases." (PMID 23144966, 2012). "Therefore, it was proposed that ectopic deposition of TG in liver mediated by FABP1 may contribute to the insulin resistance in a certain respect." (PMID 23144966, 2012). "Despite the upregulation of genes involved in fatty acid synthesis (Fasn and Scd-1) and fatty acid uptake (Fabp1 and Fabp4), cadmium exposure did not lead to insulin resistance or hepatic lipid accumulation, and instead, it improved glucose tolerance." (PMID 39839416, 2024).
colorectal cancer (14 papers, 2019 to 2025). A primary or metastatic malignant neoplasm that affects the colon or rectum. "FABP1 has a role in the regulation of inflammation and has been linked with the immune microenvironment of certain colorectal carcinomas." (PMID 40631286, 2025). "In colorectal cancer, reduced FABP1 expression was linked to poor-grade, right-sided tumor location, microsatellite instability (p < 0.0001 each), and absence of BRAF V600E mutations (p = 0.001), but unrelated to pT and pN status." (PMID 35951102, 2022). "Notably, studies have demonstrated that loss of FABP1 in colorectal cancer correlates with increased lymph node metastasis." (PMID 40694956, 2025). "In studies of cancers such as HCC and colorectal cancer, it has also been found that a high incidence of cancer is correlated with low expression of FABP1, which might be associated with the bilirubin-FABP1 interactions described previously." (PMID 40291905, 2025). "Low expression of FABP1 was found in the early-stage colorectal cancer and 93% of microsatellite unstable colorectal cancers." (PMID 35799608, 2022). "FABP1 was previously reported to be consistently downregulated in 20 colorectal cancer samples by 2D-PAGE analysis." (PMID 34563043, 2021). "The low expression of FABP1 in adenoma was related to the occurrence and development of colorectal cancer." (PMID 34957220, 2021). "Furthermore, reduced FABP1 expression has been documented in MSI-high (microsatellite instability-high) colorectal cancers, potentially attributable to the IFNγ-mediated suppression of PPARG within their highly immunoreactive microenvironment." (PMID 40694956, 2025). "FABP1 and FABP6 are strongly expressed in colorectal cancer tissues, with overexpression of FABP6 protein was found to be associated with poorer overall survival (OS) in colorectal cancer patients." (PMID 35783014, 2022). "Previous studies based on several cancer cells and animal models had found that the inactivation of TRIB3 regulated Akt pathway and enhanced tumor development, while FABP1 was significantly downregulated in some subtypes of colorectal cancer due to the influence of immune microenvironment." (PMID 34957220, 2021). "A positive FABP1 immunostaining in an adenocarcinoma in the lung may therefore be highly suggestive of an extra-pulmonary tumor origin and favor a metastasis derived from a colorectal cancer or another cancer of the gastrointestinal tract." (PMID 35951102, 2022).
liver disease (14 papers, 2019 to 2025). "GWAS of genes and proteins in sirtuin signaling and the four activated networks we identified show a single gene, FABP1, that has been reported to be associated with alanine aminotransferase levels, a marker of liver disease." (PMID 34861817, 2021). "Many studies have also proved the association between FABP1 and liver diseases." (PMID 36277716, 2022). "Furthermore, FABP1 plays important roles in changes of cellular lipid metabolic homeostasis that are associated with liver diseases, such as NAFLD, viral hepatitis, cirrhosis, and HCC." (PMID 35655171, 2022). "Here, we have shown that GSTA1 binds directly to FABP1, and higher expression of GSTA1 causes degradation of FABP1, which can alleviate liver diseases." (PMID 38791126, 2024). "Numerous reports note that FABP1 is overexpressed in the early stage of liver disease and downregulated in advanced liver disease." (PMID 33670590, 2021). "The suppression of FABP1 has been shown to potentially exacerbate lipotoxicity and liver disease progression." (PMID 33670590, 2021). "Despite the strong evidence showing the effect of serum FABP1 concentration on liver diseases, the biological mechanisms by which FABP1 is involved in the pathogenesis of NAFLD are not well understood." (PMID 32038102, 2020). "In the absence of similar data for comparison, we can cite studies which showed crucial role of FABP1 in other systemic diseases, especially in renal and liver disorders." (PMID 30993401, 2019). "On the basis of these reports, we think that endogenous FABP1 from hepatocytes may play a significant pathophysiological role in liver disease, and that further studies are required to ascertain the role of FABP1 in patients presenting with NAFLD." (PMID 32038102, 2020). "Data from experimental models show that FABP1 silencing results in intrahepatic TAG accumulation and the development of liver disease, while FABP1 can also act as a transcription factor activating genes contributing to TAG accumulation." (PMID 37569847, 2023). "Increased FABP1 levels were also observed in CHB and NAFLD, while reduced expression served to effectively protect against hepatocyte steatosis and injury, providing a potential treatment strategy for liver diseases." (PMID 32082163, 2019). "FABP1 offers superior characteristics regarding tissue distribution and kinetics compared to ALT, and it is involved in numerous metabolic disease processes, including those of liver disease, cancer, diabetes, obesity, and atherosclerosis." (PMID 32082163, 2019).
metabolic syndrome (14 papers, 2012 to 2025). A cluster of metabolic risk factors for CARDIOVASCULAR DISEASES and TYPE 2 DIABETES MELLITUS. "The Thr94Ala polymorphism in FABP1 is a susceptibility site for atherothrombotic cerebral infarction among Japanese patients with metabolic syndrome." (PMID 37091779, 2023). "Moreover, numerous genes associated with lipid metabolism have been found to influence the risk of cardiovascular disease and dyslipidemia in the general population, including the fatty acid binding protein 1 gene (FABP1, OMIM*134650)." (PMID 36143124, 2022). "Eradication therapy:Can partially reverse dyslipidemia.Is accompanied by the downregulation of key lipid regulatory genes (e.g., FABP1, MTP).Consistently increases HDL-C and apolipoprotein A1 (ApoA1) levels." (PMID 41158522, 2025). "As a result, both FABP1 and FABP2 are associated with diseases accompanied by dysregulated lipid levels, such as metabolic syndrome, non-alcoholic fatty liver disease, and type 2 diabetes." (PMID 37091779, 2023). "Studies on FABPs revealed that the plasma levels of Fabp4 were elevated in metabolic syndrome patients and the Fabp1 null mice showed sex- and age-dependent weight gain as well as increased fat tissue mass." (PMID 35321016, 2022). "Elevated FABP1 levels are associated with an increased risk of cardiovascular disease (CVD) and metabolic syndromes." (PMID 26439934, 2015). "FABP1 levels were also elevated with an increasing number of components of the metabolic syndrome (p for trend <0.001)." (PMID 23144966, 2012). "Furthermore, there was a gene–gene interaction between FOXO3 rs2802292 and FABP1 rs2241883 regarding the diagnosis of dyslipidemia by K/DOQI (TBA 0.59, p-value 0.021)." (PMID 36143124, 2022). "Furthermore, FABP1 is closely related to the occurrence and development of other metabolic syndromes." (PMID 36277716, 2022). "This study demonstrated that FABP1 in the XXZ group of patients with acute ischemic stroke was predominantly associated with the “cellular lipid metabolic process” and “response to lipid,” aligning with both domestic and international research on FABP1 and dyslipidemia." (PMID 38090270, 2023).
Hypertension (13 papers, 2011 to 2026). The presence of chronic increased pressure in the systemic arterial system. "Three of them (Crp, Fabp1, and Ucp1), known as associated with hypertension, were expressed only in adrenal glands from hypertensive rats." (PMID 28105924, 2016). "Three of these genes (Crp, C-reactive protein, pentraxin-related; Fabp1, fatty acid binding protein 1, liver; Ucp1, uncoupling protein 1 (mitochondrial, proton carrier)) are known as related to hypertension development." (PMID 28105924, 2016). "In humans, FABP-1 polymorphisms have been associated with increased levels of fasting triglycerides/LDL in females and urinary FABP-1 excretion is associated with hypertension and coronary artery disease risk factors." (PMID 21251264, 2011). "According to previous investigations, some conditions like hyperglycemia, hypertension, proteinuria, and toxin-induced damage to kidney proximal tubule cells could increase the urinary excretion of FABP1 and consequently, reduce renal levels of this protein." (PMID 34215202, 2021). "Various pathological conditions including hyperglycemia, hypertension, proteinuria, and toxin-induced injury to the proximal tubule cells may result (either through the regulation of gene expression or directly) in an increase in the excretion of urine-derived FABP1 21,22." (PMID 32922199, 2020).
Cirrhosis (11 papers, 2016 to 2024). A chronic disorder of the liver in which liver tissue becomes scarred and is partially replaced by regenerative nodules and fibrotic tissue resulting in loss of liver function. "Network 2 was persistent in viral hepatitis, cirrhosis, and HCC, with three potential hub genes (FABP1, SGK2, and HNF4A)." (PMID 38302914, 2024). "To evaluate whether FABP1, SGK2, and HNF4A related to cirrhosis and HCC, we examined the methylation levels of these gene using the GSE60753 dataset." (PMID 35655171, 2022).